SLC2A1 (solute carrier family 2 member 1)
Diseases named in the same sentence as SLC2A1 in open-access papers (continued):
Sharing a sentence is not in itself a finding about the gene and the disease.
GLUT1 deficiency syndrome (10 papers, 2015 to 2026). "Other forms of genetic epilepsy include Angelman’s syndrome, POLG1 mutation, CDKL5 disorder, SLC2A1 (Glut1 deficiency syndrome), ring chromosome 20, and Dup 15q syndrome, among others." (PMID 38883088, 2024). "Investigators from Pavia, Rho, Brescia and Milan, Italy, studied 22 patients diagnosed with GLUT1 deficiency syndrome (GLUT1DS) to document clinical or genetic differences between patients with familial SLC2A1 gene mutations (n=11) and those with sporadic mutations (n=11)." (PMID 26933557, 2015). "Interestingly, the metabolic abnormalities observed in PHD mirror those seen in GLUT1 Deficiency Syndrome (GLUT1DS), a rare neurological disorder caused by mutations in the SLC2A1 gene." (PMID 40908995, 2025).
intrauterine growth restriction (10 papers, 2013 to 2025). "Due to its abundance and distribution, SLC2A1 is considered the primary glucose transporter within the placenta, but is supported by SLC2A3, which has a higher affinity and transport capacity, at least during the first half of gestation or in some cases of intrauterine growth restriction." (PMID 38474355, 2024).
preeclampsia (10 papers, 2017 to 2025). Preeclampsia is a hypertensive disorder of pregnancy that is characterized by new-onset hypertension with proteinuria presenting after 20 weeks of gestation, and depending on mild or severe forms may initially present with severe headache, visual disturbances, and hyperreflexia. "Of note, candidate-gene approaches reported a lower methylation level of two genes, solute carrier family 2 member 1 (SLC2A1) and basic helix-loop-helix family member e40 (BHLHE40), in the placental tissue of pregnancies complicated by severe preeclampsia." (PMID 41361850, 2025). "In addition, our STRING analysis revealed the potential for interaction between glucose transporter GLUT1 and GLUT3 (SLC2A1, SLC2A3) and inflammatory mediators enriched in the plasma of preeclampsia patients." (PMID 35455936, 2022).
dementia (9 papers, 2014 to 2024). Loss of intellectual abilities interfering with an individual's social and occupational functions. "This case–control study involved the Japanese cohort population to determine the association between VC transporter genes (SLC23A2, SLC2A1, and SLC2A3) and APOE4-associated risk of developing cognitive decline (MCI or dementia)." (PMID 34780525, 2021). "Results of association analysis of three functional variants of SLC2A1 and SLC23A2 with cognitive decline (MCI or dementia)." (PMID 34780525, 2021).
depression (9 papers, 2016 to 2024). "We identified two risk genes, SLC2A1 for EHR-defined depression (OR = 6.01, 95% CI = 3.03–11.94, p = 2.96 × 10−7) and NOG (OR = 8.43, 95% CI = 3.50–20.33, p = 2.03 × 10−6) for Psypsy-defined depression through damaging missense variant burden association analysis in UKB whole-exome sequencing data." (PMID 38409228, 2024). "In UKB, the SLC2A1 damaging missense variant burden also showed consistent direction of effect on all seven depression definitions, albeit the associations were not significant for depression definitions other than EHR-defined depression." (PMID 38409228, 2024). "Finally, we showed suggestive findings of 2 genes, SLC2A1 and NOG, associated with different depression definitions through gene-based missense burden, but not through PTV burden." (PMID 38409228, 2024).
Epileptic encephalopathy (9 papers, 2019 to 2025). A condition in which epileptiform abnormalities are believed to contribute to the progressive disturbance in cerebral function. "On the other hand, mutations in SLC2A1, which codes for Glut1 and is associated with severe epileptic encephalopathy." (PMID 37047055, 2023). "SLC2A1, also known as GLUT1, encodes a 492-amino acid protein and contains 10 exons for producing of the major glucose transporter in the brain and erythrocytes, which is believed to contribute to rare and severe epileptic encephalopathy." (PMID 40217359, 2023).
Nephropathy (9 papers, 2017 to 2025). A nonspecific term referring to disease or damage of the kidneys. "Literature has also suggested that rs1385129 (in SLC2A1) might increase susceptibility to nephropathy." (PMID 40356983, 2025). "In addition, genetic variations of SLC2A1 also affect nephropathy and may be involved in the risk of micro- and macroalbuminuria in adult European Americans patients with T2DM." (PMID 34948317, 2021). "Association between SLC2A1 gene variants and T2DM- nephropathy for the additive and co-dominant models." (PMID 30353771, 2018).
papillary thyroid cancer (9 papers, 2013 to 2025). "Significantly, loss of NOX4 in human papillary thyroid cancer cells decreases HIF1α targeting genes such as SLC2A1 and CA9, highlighting the potential importance of NOX4-mediated metabolic reprogramming in thyroid tumor." (PMID 30367082, 2018).
rheumatoid arthritis (9 papers, 2013 to 2026). A chronic, systemic autoimmune disorder characterized by inflammation in the synovial membranes and articular surfaces. "From single‐cell RNA‐sequencing analysis of synovial tissues isolated from rheumatoid arthritis patients, we identified that the expression of SLC2A1 and SLC16A3 increased along with concentrations of proinflammatory factors and glycolytic enzymes." (PMID 36354099, 2022).
bladder tumors (8 papers, 2018 to 2025). "Focusing on top-ranked glycoproteins, GLUT1, encoded by the SLC2A1 gene, is a pivotal membrane glucose transporter frequently overexpressed in more aggressive bladder tumours." (PMID 34108014, 2021). "We found that seven of these genes, IGFBP3, VEGF, CCNG2, NDRG1, PFKFB3, ADM and SLC2A1, were also upregulated in MIBC and/or NMIBC in our study, suggesting parallel hypoxia-induced expression changes with primary bladder tumour tissue." (PMID 40867253, 2025).
Cerebral ischemia (8 papers, 2014 to 2025). Restriction of arterial blood supply to the brain associated with insufficient oxygenation to support the metabolic requirements of the tissue. "During cerebral ischemia, glucose transporters such as SLC2A1 (Glut-1) are upregulated, by which BCECs try to take up the remaining glucose for stabilizing the energy balance." (PMID 32138745, 2020).
pyruvate dehydrogenase deficiency (8 papers, 2019 to 2025). A rare neurometabolic disorder characterized by a wide range of clinical signs with metabolic and neurological components of varying severity. "These included initiation of a ketogenic diet to patients with pyruvate dehydrogenase deficiency (mutations in PDHA1, PDHB, DLD), AGC1 deficiency (mutations in SLC25A12), and GLUT1 deficiency (mutations in SLC2A1)." (PMID 33726816, 2021).
cholangiocarcinoma (7 papers, 2007 to 2025). A carcinoma that arises from the intrahepatic biliary tree (intrahepatic cholangiocarcinoma) or from the junction, or adjacent to the junction, of the right and left hepatic ducts (hilar cholangiocarcinoma). "PDT can up-regulate the expression of SLC2A1, SLC2A6, and SLC7A5 and inhibit the expression of ZEB1, and four ferroptosis-sensitive genes are associated with the prognosis of patients with cholangiocarcinoma." (PMID 37894410, 2023). "A study obtained four genes associated with ferroptosis (SLC2A1, SLC2A6, SLC7A5, ZEB1) by analyzing RNA-seq data after PDT in cholangiocarcinoma." (PMID 37894410, 2023).
colitis (7 papers, 2019 to 2025). Inflammation of the colon. "For example, there was significant induction of Traf1, Tnfrsf9, Hif1a, Slc2a1 and Pim1 in TREG clusters in CPI colitis in comparison with TREG clusters in control mice." (PMID 37872166, 2023).
generalized epilepsies (7 papers, 2017 to 2025). "The glucose transporter GLUT1 plays an essential role in capillary to brain glucose transport and mutations in the SLC2A1 gene that encodes GLUT1 lead to deficiency of the transporter and cause several types of generalized epilepsy." (PMID 30349461, 2018). "Early onset absence epilepsy (before four years of age), myoclonic–atonic epilepsy, idiopathic generalized epilepsy, childhood absence epilepsy, and eyelid myoclonia epilepsy could be associated with pathogenic SLC2A1 mutations." (PMID 40048124, 2025).
Hypertension (7 papers, 2009 to 2025). The presence of chronic increased pressure in the systemic arterial system. "In total, 12 markers in 7 genes (ADRA2A, LEP, LEPR, PTGER3, SLC2A1, SLC4A2, SLC8A1) revealed considerable association (P<10−3) either with SBP, DBP, and/or hypertension (HYP)." (PMID 19562039, 2009).
invasive carcinoma (7 papers, 2013 to 2022). A carcinoma that is not confined to the epithelium, and has spread to the surrounding stroma. "Like SLC2A1, LDHA was found to increase expression during the transition from precancerous lesions to invasive carcinomas, and multiple studies have confirmed that LDHA is closely related to tumor initiation and progression." (PMID 34977159, 2021).
ischemic stroke (7 papers, 2019 to 2025). A stroke disorder caused by obstruction of blood flow to the brain, due to thrombotic (local blood clot formation) or embolic (due to a blood clot or other material traveling from another site) event. "Among the possible regulatory genes for glucose transportation, Slc2a1, which is the regulatory gene for GLUT1, was highly expressed in normal astrocytes, but vastly decreased in 12 h after ischemic stroke, and upregulated at 24 h." (PMID 35535357, 2022).
Seizure (7 papers, 2021 to 2025). A seizure is an intermittent abnormality of nervous system physiology characterized by a transient occurrence of signs and/or symptoms due to abnormal excessive or synchronous neuronal activity in the brain.
cognitive decline (6 papers, 2014 to 2024). "In the present study, we aimed to examine the effects of functional variants of VC transporter genes expressed in the brain (SLC2A1, SLC2A3, and SLC23A2) on APOE4-associated risk of developing cognitive decline." (PMID 34780525, 2021). "Contrary to SLC23A2, in the stratified analysis by genotype in SLC2A1, APOE4 was shown to have a significant risk of cognitive decline in the high expression groups of SLC2A1 (rs710218 and rs841851), but not in the low expression groups." (PMID 34780525, 2021). "We hypothesized that genetic variants of VC transporters (SLC23A2, SLC2A1, and SLC2A3) expressed in the brain could affect the risk of developing APOE4-associated cognitive decline." (PMID 34780525, 2021). "The results showed that the functional variants of SLC2A1 and SLC23A2 may affect or modify the risk of developing APOE4-associated cognitive decline." (PMID 34780525, 2021). "For this purpose, we found three functional SNVs associated with the changes in SLC2A1 and SLC23A2 expression by searching several publicly available databases, and analyzed the effects of these variants on APOE4-associated risk of developing cognitive decline." (PMID 34780525, 2021). "To investigate the relationship between cognitive decline and brain VC level in humans, we need to focus on the roles of brain-expressed VC transporters (SLC23A2, SLC2A1, and SLC2A3) in human cognitive function." (PMID 34780525, 2021).
De Vivo disease (6 papers, 2011 to 2025). "In humans, variants of SLC2A1 are associated with glucose transporter type 1 deficiency syndrome (GLUT1DS; OMIM# 606777)." (PMID 40217381, 2024).
Hepatic steatosis (6 papers, 2018 to 2025). Steatosis is a term used to denote lipid accumulation within hepatocytes. "Genetic variants in “glucokinase regulatory protein” (GCKR) gene, “solute carrier family 2-member 1” (SLC2A1) gene, and “17-beta hydroxysteroid dehydrogenase 13” (HSD17B13) gene, have also been identified in patients with fatty liver disease." (PMID 36976456, 2023). "Bio-informatic prediction of miR-21 potential mRNAs target revealed putative genes involved in both HCC and in Fatty Liver disease, including PTEN33, and SLC2A1 and PPARA that also showed reduced expression after sodium oleate treatment in dHepaRG cells." (PMID 30206377, 2018).
acute myeloid leukemia (5 papers, 2020 to 2025). Acute myeloid leukemia (AML) is a group of neoplasms arising from precursor cells committed to the myeloid cell-line differentiation. "On the contrary, the expression level of SLC2A1 was downregulated in acute myeloid leukemia (LAML) and skin cutaneous melanoma (SKCM)." (PMID 36712872, 2022). "And SLC2A1 has been reported to induce chemotherapy resistance in acute myeloid leukemia, but its role in drug-resistant NSCLC has not been elucidated." (PMID 41309566, 2025).
cervical squamous cell carcinoma (5 papers, 2015 to 2024). A squamous cell carcinoma arising from the cervical epithelium. "Therefore, high SLC2A1 expression may be considered a risk factor for cervical squamous cell carcinoma." (PMID 39526479, 2024). "Many tools, such as Kaplan–Meier and Cox regression analyses, have been used to confirm that the expression of SLC2A1 is related to the prognosis of patients with cervical squamous cell carcinoma." (PMID 39526479, 2024). "In our study, western blotting results showed that SLC2A1 was upregulated in cervical squamous cell carcinoma." (PMID 39526479, 2024). "SLC2A1, ANO6, and TXNIP are associated with cervical squamous cell carcinoma and may be ferroptosis‐related markers of the disease." (PMID 39526479, 2024). "SLC2A1, ANO6, and TXNIP are associated with cervical squamous cell carcinoma and may serve as ferroptosis‐related markers of the disease." (PMID 39526479, 2024). "Meanwhile, SLC2A1, ANO6, and TXNIP are associated with cervical squamous cell carcinoma and may be ferroptosis‐related markers of this disease." (PMID 39526479, 2024). "Interestingly, TXNIP exhibited a positive correlation with the survival rate and prognosis of patients with cervical squamous cell carcinoma, whereas ANO6 and SLC2A1 showed the opposite trend; both genes were negatively correlated with the survival rate and prognosis of patients." (PMID 39526479, 2024).
invasive ductal breast carcinoma (5 papers, 2012 to 2025). The most common type of invasive breast carcinoma, accounting for approximately 70% of breast carcinomas. "In the Zhao Breast dataset, SLC2A1 was overexpressed in invasive ductal breast carcinoma and lobular breast carcinoma compared with that in the normal samples, with a fold change of 2.800 and 2.075 separately." (PMID 34525987, 2021). "In Zhao Breast dataset, SLC2A1 was overexpressed in invasive ductal breast carcinoma compared with normal tissues with a fold change of 2.800." (PMID 34488531, 2021).
skin cutaneous melanoma (5 papers, 2008 to 2025). "For instance, SLC2A1 levels were upregulated in most tumors but significantly downregulated in skin cutaneous melanoma." (PMID 38420162, 2024).
acute myocardial infarction (4 papers, 2020 to 2025). Necrosis of the myocardium, as a result of interruption of the blood supply to the area. "Elevated expression levels of RAC1, IQGAP1, MYL6, DBN1, SLC2A1 and SLC2A3 were observed in acute myocardial infarction patients compared to healthy controls, suggesting a strong association with disease progression and indicating their potential as novel therapeutic targets." (PMID 40672380, 2025).
adrenocortical carcinoma (4 papers, 2015 to 2021). "Accordingly, pediatric cancers overexpressing SLC2A1, like adrenocortical carcinomas and liver vascular tumors, have worse prognosis than SLC2A1-negative tumors." (PMID 33810575, 2021).
cervical tumor (4 papers, 2013 to 2018). "High expression of HIF1A and its target proteins glucose transporter SLC2A1 (GLUT1) and pH regulator CA9 has been found in cervix tumors that were identified as hypoxic by pimonidazole staining or electrode measurements." (PMID 28804704, 2017).
chordoma (4 papers, 2014 to 2025). Chordomas are rare malignant tumors arising from embryonic remnants of the notochord in axial skeleton. "Genes were selected to represent both those functionally connected to other chordoma dependency genes (PTPN11, FANCM, ADAR, PRKRA, SOX9, SRRM2, SLC2A1, and SLC7A5), as well as those with putatively unique effects (LUC7L2 and CDK6)." (PMID 37024492, 2023).
colorectal adenocarcinoma (4 papers, 2008 to 2024). The most common type of colorectal carcinoma. "In colorectal adenocarcinoma, SLC2A1(also called Glut1) expression has been associated with poor survival, tumor grade, stage, metastasis, reduced immune cell activity, and poor prognosis." (PMID 39682235, 2024).
episodic ataxia (4 papers, 2015 to 2021). "In the episodic ataxia cohort, one family was identified with a mutation in the PRRT2 gene, one with a defect in the SLC2A1 gene and two familial hemiplegic migraine families were identified, one with a PRRT2 mutation and one with a novel PNKD mutation." (PMID 26598494, 2015). "SLC2A1 mutations were associated with variable phenotypes including paroxysmal kinesigenic dyskinesia, paroxysmal non-kinesigenic dyskinesia, episodic ataxia and myotonia and we identified a novel PNKD gene deletion in familial hemiplegic migraine." (PMID 26598494, 2015).
hyperthyroidism (4 papers, 2020 to 2024). Overactivity of the thyroid gland resulting in overproduction of thyroid hormone and increased metabolic rate. "As a link to increased energy demands with hyperthyroidism, we checked the expression of Slc2a1, Slc2a3 and Slc2a4 encoding for class I glucose transporters GLUT1, GLUT3 and GLUT4, respectively, that facilitate glucose transport across the cell membrane." (PMID 38719881, 2024).
infantile epilepsy (4 papers, 2019 to 2025). "Heterozygous forms of the SLC2A1 gene, causing partial deficiency of GLUT1, are associated with intractable infantile epilepsy." (PMID 40806521, 2025).
renal fibrosis (4 papers, 2022 to 2026). A final common manifestation of a wide variety of chronic kidney diseases characterized by glomerulosclerosis and tubulointerstitial fibrosis. "RUNX1 subsequently activated HK1 and SLC2A1, which accelerated glycolysis and renal fibrosis of DKD." (PMID 41694585, 2026).
Anxiety (3 papers, 2022 to 2024). Intense feelings of nervousness, tension, or panic often arise in response to interpersonal stresses. "On the other hand, hyperkinesis in dark phase and anxiety, clearly reported for both models, could be connected with deregulated various clock‐controlled metabolic genes involved in insulin signaling and mitochondrial function, for example, Igf1r and Slc2a1." (PMID 39604147, 2024).
endometrial adenocarcinoma (3 papers, 2015 to 2022). "It was also demonstrated that SLC2A1 over-expression was associated with several clinicopathologic parameters of endometrium and endometrial adenocarcinoma." (PMID 26193257, 2015).
gastric tumor (3 papers, 2012 to 2025). "Here, SLC2A1 was significantly upregulated only in EC, and was the sole gene overexpressed in esophageal as compared to gastric tumors." (PMID 32630408, 2020). "Moreover, factors indicative of high proliferative capacity—Ki67 and ODC1—were independent predictors of SLC2A1 expression in non-cancerous tissue and gastric tumor, respectively." (PMID 32630408, 2020).
Jeavons syndrome (3 papers, 2022 to 2025). "Therefore, SLC2A1, as the causative gene in the photosensitive model of Jeavons syndrome, might be a candidate gene for photosensitive epilepsy." (PMID 36034301, 2022).
metastatic cancers (3 papers, 2010 to 2021). A carcinoma which has spread from the original site of growth to another anatomic site. "In the EHC, SLC2A1 expression was evaluated in 189 normal mucosa, 279 primary cancer and 58 metastatic cancer samples." (PMID 33735188, 2021).